RNU6ATAC22P (RNA, U6atac small nuclear 22, pseudogene)
Gene: Small nuclear RNA gene on chromosome 22 (41,722,043 to 41,722,131, reverse strand). Ensembl gene ENSG00000252603.
Homologues: Paralogues in human: RNU6ATAC (83% identical), RNU6ATAC7P (78% identical), RNU6ATAC21P (76% identical), RNU6ATAC6P (74% identical), RNU6ATAC8P (74% identical), RNU6ATAC27P (73% identical), RNU6ATAC41P (73% identical), RNU6ATAC39P (62% identical), RNU6ATAC19P (54% identical).